MMP9 (matrix metallopeptidase 9)
Diseases named in the same sentence as MMP9 in open-access papers (continued):
Sharing a sentence is not in itself a finding about the gene and the disease.
skin aging (16 papers, 2017 to 2026). The gradual irreversible changes in structure of skin that occur as a result of the passage of time.. "On the other hand, PM2.5 has been shown to induce MMP-2 and MMP-9 expression in human keratinocytes and cause skin aging." (PMID 32922544, 2020). "In addition, PM-induced oxidative stress promoted via the production of ROS and subsequent increase in the activity of matrix metalloproteinases (MMPs), including MMP-1, MMP-2, and MMP-9, can cause skin aging as a consequence of the degradation of collagen." (PMID 30669248, 2019). "Although we identified Fos and MMP9 as the targets of radiofrequencies in skin aging treatment, validation of these targets using either genetic or pharmacologic manipulation has not yet been fulfilled." (PMID 40362699, 2025). "Matrix metalloproteinases (MMPs), particularly MMP-1 and MMP-9, play a key role in extracellular matrix (ECM) degradation and are closely associated with the progression of skin aging." (PMID 41375950, 2025). "The results suggested that LNF is non-toxic to dermal fibroblast cells and can inhibit the secretion of MMP1, MMP9, IL-6 and IL-8 upon UV-induced skin aging." (PMID 35215366, 2022). "Concurrently, squid ink polysaccharides decrease the ROS induced up-regulation of MMP1 and MMP9 to decrease MMP-mediated skin aging." (PMID 32009967, 2019). "MMP-1 and MMP-9 play an important role in type I collagen synthesis, inhibition of its expression is a way to prevent or mitigate UV-induced skin aging, and secretion of type I procollagen is important to provide structural support of skin." (PMID 31762729, 2019). "At the same time, SIP decreased the ROS induced up-regulation of MMP1 and MMP9 to ease MMP-mediated skin aging." (PMID 32009967, 2019). "Through the MAPK signaling pathways, AP-1 controls the expression of MMPs, especially MMP-1, MMP-2, and MMP-9, in inflammation-induced skin aging." (PMID 28900534, 2017). "Therefore, ELISA results can prove that more than 50 μM concentration of abalone peptide can increase the secretion of type I procollagen in cells, reduce the secretion of MMP-1 and MMP-9, and prevent skin aging." (PMID 31762729, 2019). "In addition, histopathological examination showed an improvement in the cohesiveness of the stratum corneum, an increase in glycosaminoglycans, and a decrease in the amount of MMP-9, which is responsible for the breakdown of collagen and acceleration of skin aging." (PMID 40095547, 2025). "Hence, LNF could reduce the secretions of MMP1 and MMP9 upon UV exposure, and subsequently prevent photo-induced skin aging." (PMID 35215366, 2022). "First, harringtonine markedly suppressed the expression of matrix metalloproteinases (MMP-1, MMP-2, and MMP-9), which are critical mediators of ECM degradation and play central roles in the pathogenesis of skin aging and photoaging." (PMID 40864795, 2025). "The accumulation of ROS has been reported to induce skin aging through the expression of MMPs, including MMP-1, MMP-2, and MMP-9." (PMID 30669248, 2019). "As MMP-2 and MMP-9 have also been reported to be involved in skin aging through the degradation of collagen, we analyzed the expression levels of MMP-2 and MMP-9 protein and found that these were also increased by PM2.5 treatment and decreased by FFO pretreatment." (PMID 30669248, 2019).
ameloblastoma (15 papers, 2012 to 2024). The most common odontogenic tumor, arising from the epithelial component of the embryonic tooth and usually affecting the molar-ramus region of the mandible or maxilla. "‘Chi Square’ Test was applied to find the association of MMP-9 and E-Cadherin with histological variants of ameloblastoma." (PMID 35035427, 2022). "The purpose of this study was to determine the immuno-expression of markers such as MMP-9 and E-Cadherin in different sub-types of ameloblastoma and establish their correlation with histological variants." (PMID 35035427, 2022). "Overexpression of MMP-2 and MMP-9 was associated with the infiltrative behaviour of ameloblastomas, as well as that of several malignant neoplasms." (PMID 22866959, 2012). "Therefore, the purpose of this study was to investigate the association between MMP-2 and MMP-9 methylation and their mRNA transcription and protein expression in ameloblastomas." (PMID 22866959, 2012). "This study was conducted to determine the expression of immuno-histochemical markers including E-Cadherin and MMP-9 in different histological types of ameloblastoma for gauging and predicting the aggressiveness and behavior of this tumor in our population." (PMID 35035427, 2022). "MMP-9 is considered in the local invasion of ameloblastoma primarily by monitoring extracellular matrix whereas, E-cadherin is concerned in the control of the Ameloblastic local manners by its role in epithelial-mesenchymal transition process." (PMID 35035427, 2022). "The effect of MMP-9 and E-cadherin in ameloblastoma is aggressive in nature and effectiveness was seen in subtypes of ameloblastoma." (PMID 35035427, 2022). "EGFR functions downstream of EGF and stimulates the migration and invasion of human ameloblastoma in an MMP-9 dependent mechanism." (PMID 29029486, 2017). "All of the ameloblastomas showed MMP-9 protein expression and were mostly unmethylated for MMP-9, so it was not possible to assess if the transcription of the gene was correlated with its methylation status." (PMID 22866959, 2012). "Our findings suggest that expression of MMP-9 is increased in ameloblastomas and is possibly modulated by unmethylation of the gene." (PMID 22866959, 2012). "We investigated the methylation status of the genes MMP-2 and MMP-9 in addition to mRNA transcription and protein expression in ameloblastomas." (PMID 22866959, 2012). "In conclusion, our study provides new insights into the epigenetic regulation of MMPs in ameloblastomas and points to the hypomethylation of MMP-9 as a possible mechanism involved in the increased transcription of the gene in this tumour." (PMID 22866959, 2012). "Asimismo, se ha descrito la participación de MMP-9 en la invasión local del ameloblastoma." (PMID 39444727, 2024). "MMP-9 may be used in future as a potential marker to serve as an indicator and utilize in monitoring degree of local aggressiveness of Ameloblastoma." (PMID 35035427, 2022). "Bone degradation around ameloblastoma may be due to MMP‐9 in osteoclasts but this phenomenon might be an independent process and needs further investigations." (PMID 32985799, 2021). "Other group reported that TNF‐α induced the expression IL‐6 and MMP‐9 from ameloblastoma cells." (PMID 29226086, 2017). "In that study, we have shown that Wnt‐3a promotes the expression of MMP‐9 from ameloblastoma cells." (PMID 29226086, 2017). "Accordingly, our data suggest that an unmethylated profile of the MMP-9 gene in ameloblastomas may be a permissive event allowing the binding of transcription factors to DNA, thus favouring MMP-9 gene transcription." (PMID 22866959, 2012). "Methylation analysis was performed by both methylation-specific polymerase chain reaction (MSP-PCR) and restriction enzyme digestion to evaluate the methylation profile of MMP-2 and MMP-9 in 12 ameloblastoma samples and 12 healthy gingiva fragments, which were included as controls." (PMID 22866959, 2012).
ameloblastoma (continued). "Higher expression levels of MMP-9 were found in ameloblastomas compared to healthy gingiva." (PMID 22866959, 2012). "In the present study, we hypothesised that methylation may regulate the expression of MMP-2 and MMP-9 in ameloblastomas." (PMID 22866959, 2012). "Similarly, an increased frequency of unmethylated MMP-9 of specific CG sites digested by HhaI was identified in the ameloblastomas." (PMID 22866959, 2012). "Almost all of the ameloblastoma samples showed an unmethylated profile for MMP-9." (PMID 22866959, 2012). "The DNA methylation status of these MMPs was investigated in 12 ameloblastomas (11 solid and one unicystic), and in healthy gingival tissue, and the authors indicated that hypomethylation of MMP-9 might be a mechanism involved in the increased transcription of the gene in this tumor." (PMID 33680332, 2021). "Furthermore, it was suggested that increased expression of MMP-9 may be involved in the proliferation and invasive behaviour of ameloblastomas." (PMID 22866959, 2012). "However, our study suggests that the increased transcription of MMP-9 in ameloblastomas could possibly be influenced by unmethylation of the gene." (PMID 22866959, 2012). "In ameloblastoma, SPARC expression showed a significant correlation with MMP-9 expression, suggesting that SPARC participates in local aggressiveness of this tumor." (PMID 38347494, 2024). "Activation of EGFR can promote cell migration and invasion in ameloblastoma cells by enhancing MMP2 and MMP9 activity." (PMID 39100096, 2024). "Several studies also demonstrated that MMPs like MMP-1, MMP-2, MMP-7, MMP-9 and MMP-14 are involved in ECM degradation in the invasion of ameloblastoma [16,21,22,]." (PMID 35243014, 2022). "The invasive properties of ameloblastoma cells and their ability to resorb bone were investigated by assessing the expression of MMP-2, MMP-9, RANK, and RANKL16 prior to initiation of invasion." (PMID 34916549, 2021). "The ameloblastomas showed a high frequency of unmethylated MMP-2 and MMP-9, whereas the healthy gingival samples presented a sharp prevalence of methylated MMPs." (PMID 22866959, 2012). "All of the ameloblastoma samples showed expression of MMP-2 and MMP-9 proteins, as verified by zymography." (PMID 22866959, 2012). "While AM-3 cells spontaneously produced high amount of MMP-9 and had potential to increase MMP-9 production in response to Wnt-3a, this study demonstrated that AM-3 ameloblastoma cells showed higher expression of MMP-2 by the treatment of MC3T3-E1 osteoblast CM." (PMID 35243014, 2022). "The ameloblastomas presented an unmethylated profile of MMP-2 and MMP-9 genes compared to gingiva." (PMID 22866959, 2012). "All ameloblastomas showed positive expression of MMP-2 and MMP-9 proteins." (PMID 22866959, 2012). "As most of the ameloblastomas were unmethylated at the MMP-9 gene, considering all of the restriction sites, it was not possible to statistically compare the transcription of the gene in the cases with or without methylated sequences." (PMID 22866959, 2012). "Neither MMP‐8 nor MMP‐9 immunoexpression could be detected in ameloblastoma cells." (PMID 32985799, 2021). "However, pro-MMP-2 and pro-MMP-9 forms were not identified in ameloblastomas." (PMID 22866959, 2012). "Because ameloblastoma tumor tissue did not express MMP‐9 with neither of the two different MM‐9 –antibodies used, our results challenge the previous studies where MMP‐9 claimed to be expressed by the tumor cells as well." (PMID 32985799, 2021).
atrial fibrillation (15 papers, 2013 to 2025). A disorder characterized by an electrocardiographic finding of a supraventricular arrhythmia characterized by the replacement of consistent P waves by rapid oscillations or fibrillatory waves that vary in size, shape and timing and are accompanied by an irregular ventricular response. "Studies have shown that MMP-9 is significantly higher in obese patients with paroxysmal atrial fibrillation than in obese patients alone." (PMID 36910669, 2023). "However, PAI-1 did not remain an independent variable in the best diagnostic model, which consisted of age, face- arm- speech test (FAST), atrial fibrillation, and three other serum markers (protein S100B, MMP-9 and IL-6)." (PMID 39001884, 2024). "Through induction of transforming growth factor beta 1 and MMP-9 (associated with myocardial matrix remodeling) and induction of myocardial fibrosis, hypoxia-inducible factor 1α and Ang II are associated with pathogenesis and maintenance of atrial fibrillation (AF)." (PMID 33855053, 2021). "With the fact that increased Sdc4 and Mmp9 have been shown to contribute to obesity-related disorders such as resistant hypertension and atrial fibrillation, the detrimental effects of Mmp9 may be at least partially mediated through its induction on Sdc4 shedding." (PMID 40180176, 2025). "Contrarily, in the group of patients with postoperative atrial fibrillation (POAF) after primary coronary artery by-pass grafting, the level of MMP-9 was decreased and TIMP-1 level increased." (PMID 36835040, 2023).
bipolar disorder (15 papers, 2012 to 2025). A disorder of the brain that causes unusual shifts in mood, energy, activity levels and the ability to carry out day-to-day tasks. "Further research is warranted to elucidate the complex associations between ADHD, first-episode major affective disorders, MMP-9, proinflammatory cytokines, and cognitive function." (PMID 40219625, 2025). "Moreover, different MMP-9 gene polymorphisms, which are associated with high MMP-9 levels, have been associated with depressive symptoms in bipolar disorder patients (rs17576) and anxiety disorders (rs3918242)." (PMID 40405318, 2025). "Additionally, no study has explored the potential association between elevated MMP-9 levels and emotional dysregulation, despite both conditions being prevalent in major affective disorders and ADHD." (PMID 40219625, 2025). "The authors found that serum MDNF, proBDNF, the ratio of BDNF/proBDNF, and interaction with MMP-9 were different between patients with bipolar disorders and healthy controls." (PMID 25089150, 2014). "While we believe that this is the first study to observe this relationship in PTSD, MPO has been positively correlated with duration of bipolar disorder, and higher MMP-9 has been reported in younger youth diagnosed with bipolar disorder compared to older adults." (PMID 37333909, 2023). "Furthermore, increased levels of MMP-9 were demonstrated in bipolar depression, suggesting that MMP-9 could contribute to BBB degradation and disease progression of bipolar patients." (PMID 34113269, 2021). "Because SED is conceptualized as a transdiagnostic endophenotype among ADHD and major affective disorders, we investigated the effects of both diagnoses (ADHD and major affective disorders) and SED on MMP-9, CRP, and IL-6 levels and on inhibitory control function." (PMID 40219625, 2025). "The reason for the change in MMP-9 only at one stage of bipolar disorder is not known." (PMID 35370878, 2022). "MMP-9 and MMP-2 expression in blood were not different between patients with bipolar disorder and control group." (PMID 35370878, 2022).
intracranial aneurysm (15 papers, 2013 to 2024). "Recently, studies have found that MMP-9 polymorphism is associated with intracranial aneurysm." (PMID 37475739, 2023). "Indeed, both CREB3L1 and MMP9 are up-regulated in intracranial aneurysm, which causes hemorrhage and is associated with MMP-mediated destabilization of the arterial wall." (PMID 25359725, 2014). "On the other hand, augmentation of MMP-9 has been observed in the lesion of intracranial aneurysm rupture in patients and a rat model." (PMID 36289761, 2022). "It has been reported that secreted protein acidic and cysteine-rich (SPARC) is highly expressed in intracranial aneurysms and is associated with the expression of EMT-related molecules (namely MMP2 and MMP9)." (PMID 34997174, 2022). "Several studies have described the pathophysiological involvement of MMP9 in intracranial aneurysms in human patients and the relationship between MMP9 and collagen fibrils." (PMID 30541770, 2018). "We found that the expression levels of SPARC, MMP-2 and MMP-9 were significantly up-regulated in intracranial aneurysms relative to the levels in normal Circle of Willis arteries." (PMID 23516489, 2013). "The western blot results showed that the expression levels of SPARC, MMP-2 and MMP-9 were significantly up-regulated in intracranial aneurysms relative to the expression levels in the normal Circle of Willis arteries." (PMID 23516489, 2013). "The results showed that SPARC, MMP-2 and MMP-9 were strongly expressed in intracranial aneurysm tissues; however, these proteins were expressed minimally or not at all in normal Circle of Willis arteries." (PMID 23516489, 2013). "The present study showed that SPARC expression in cerebral aneurysms is significantly correlated with MMP-2 and MMP-9 expression (P<0.05), and MMPs are by far the proteases that are the most closely related to the pathogenesis of intracranial aneurysms." (PMID 23516489, 2013). "Macrophage-derived MMP-9 promotes intracranial aneurysm rupture." (PMID 37223093, 2023). "Their MMP-9-mediated actions might be involved in the pathogenesis of aortic and intracranial aneurysms and their rupture." (PMID 36289761, 2022). "Our finding that mmp9 could function downstream of col22a1 is consistent with the reported role of MMP9 in the formation of intracranial aneurysm in mice." (PMID 30541770, 2018). "Combined with previous research, the present study shows that SPARC regulates MMP-2 and MMP-9 expression in human intracranial aneurysms; however, whether SPARC is an upstream or downstream regulatory factor remains to be determined." (PMID 23516489, 2013). "By reporting morphological evidence of high level of SPARC, MMP and MMP9 in these patients, our results may yield important sight into pathogenesis of intracranial aneurysms and open avenues for the investigation of new therapeutics in this disease." (PMID 23516489, 2013). "Chymase-activated MMP-9 may also contribute to the intracranial aneurysm rupture." (PMID 36289761, 2022). "Further, the role of MMP-9 could be attributed to the anti-angiogenic effect of SPARC.The role of SPARC in tumors led us to wonder whether it is also involved in the occurrence of intracranial aneurysms." (PMID 23516489, 2013). "The NLRP3/MMP9 pathway induces VSMC apoptosis and elastic fiber degradation, contributing to the progression of intracranial aneurysms." (PMID 38992615, 2024). "Clinical studies showed elevated serum levels of MMP-9 in the patients who had AAA 57,58, arterial dissection 55,56, and/or intracranial aneurysm 59-61." (PMID 34671201, 2021). "Recent studies have shown that NF-κB p65 can promote inflammatory changes and regulate MMPs (MMP-1, MMP-2, MMP-3, and MMP-9) transcription participating in the initiation and progression of AAA and intracranial aneurysm (IA)." (PMID 26918963, 2016).
intracranial aneurysm (continued). "In this study, to our knowledge we are the first to demonstrate that T1DM promotes the formation of intracranial aneurysm as well as significantly increases RAGE, MMP9 and TLR4 expression in the intracranial arterial wall compared to WT non-DM rats." (PMID 23844137, 2013). "Thirty-one intracranial aneurysms were immunohistochemically stained for SPARC, MMP-2 and MMP-9." (PMID 23516489, 2013). "The results showed that normal Circle of Willis arteries exhibited either minimal or negative staining for SPARC, MMP-2 and MMP-9; however, human intracranial aneurysms stained extensively for both SPARC and MMP-2/-9." (PMID 23516489, 2013). "The increased intracranial aneurysm formation may be regulated by inflammatory factors RAGE, MMP9 and TLR4." (PMID 23844137, 2013). "The results indicate that SPARC is widely expressed in human intracranial aneurysms, and its expression correlates with MMP-2 and MMP-9 expression, age and risk factors but not with the Hunt-Hess grade." (PMID 23516489, 2013). "The study showed that SPARC is widely expressed in intracranial aneurysms, and the expression of SPARC is significantly correlated with the expression of MMP-2 and MMP-9, which are by far the proteases that are the most closely related to the pathogenesis of intracranial aneurysms." (PMID 23516489, 2013).